AVPR2 (arginine vasopressin receptor 2)
Diseases named in the same sentence as AVPR2 in open-access papers (continued):
Sharing a sentence is not in itself a finding about the gene and the disease.
Hydrocephalus (1 paper, 2017). Hydrocephalus is an active distension of the ventricular system of the brain resulting from inadequate passage of CSF from its point of production within the cerebral ventricles to its point of absorption into the systemic circulation. "In addition, large deletions of the AVPR2 gene may also encompass the L1CAM gene, mapping adjacent to the AVPR2, and be responsible for both X-NDI and hydrocephalus." (PMID 29125546, 2017).
Immunodeficiency (1 paper, 2008). Failure of the immune system to protect the body adequately from infection, due to the absence or insufficiency of some component process or substance. "Recently, an NDI patient lacking AVPR2 and all of ARHGAP4 showed immunodeficiency characterised by a marked reduction in the number of circulating CD3+ cells and almost complete absence of CD8+ cells." (PMID 18489790, 2008). "ARHGAP4 is expressed at high levels in hematopoietic cells, and it has been reported that an NDI patient lacking AVPR2 and all of ARHGAP4 showed immunodeficiency characterised by a marked reduction in the number of circulating CD3+ cells and almost complete absence of CD8+ cells." (PMID 18489790, 2008).
lung adenocarcinoma (1 paper, 2022). A carcinoma that arises from the lung and is characterized by the presence of malignant glandular epithelial cells. "It was worth noting that the expression of RXFP1, AVPR2, ADRB1 and VIPR1 had significantly effect on the survival of patients with lung adenocarcinoma." (PMID 36032660, 2022).
neurohypophyseal diabetes insipidus (1 paper, 2019). Hereditary central diabetes insipidus is a rare genetic subtype of central diabetes insipidus (CDI) characterized by polyuria and polydipsia due to a deficiency in vasopressin (AVP) synthesis. "The pathway of Defective AVP does not bind AVPR2 causing neurohypophyseal diabetes insipidus (NDI); it is the most highlighted group term for down-regulated network." (PMID 32099601, 2019).
renal fibrosis (1 paper, 2022). A final common manifestation of a wide variety of chronic kidney diseases characterized by glomerulosclerosis and tubulointerstitial fibrosis. "In alloxan-induced DN rats, rutin ameliorated renal fibrosis and metabolic acidosis via reducing the metabolic acidosis-related genes aquaporin 2 (AQP2), aquaporin 3(AQP3), and arginine vasopressin receptor 2 (V2R)." (PMID 35408760, 2022).
selenium deficiency (1 paper, 2021). A nutritional deficiency disease resulting from inadequate selenium levels in the body, which can lead to impaired function of selenoproteins essential for antioxidant defense and thyroid hormone metabolism. "However, neither Aqp2 nor Avpr2 mRNA were affected by maternal selenium deficiency." (PMID 33769708, 2021).
X-linked inherited disorder (1 paper, 2006). "Congenital nephrogenic diabetes insipidus (NDI) is a rare X-linked inherited disorder characterized by the excretion of large volumes of diluted urine and caused by mutations in arginine vasopressin receptor 2 (AVPR2) gene." (PMID 17101063, 2006).
tumor (28 papers, 2014 to 2026). "Activation of AVPR2 promotes proliferation of clear cell renal carcinoma cell lines and is associated with tumour grade." (PMID 36998036, 2023). "We also observed that AVPR2 was associated with the majority of tumour-infiltrating immune cell markers and immune-related genes, and that the expression of CD40LG, which plays a key role in B-cell activation, was positively correlated with AVPR2." (PMID 36998036, 2023). "We also studied the potential link between AVPR2 expression and immune subtypes, promising immune biomarkers, and tumour-infiltrating immune cells in the tumour microenvironment." (PMID 36998036, 2023). "In view of the crucial role of immune checkpoint molecules in the regulation of tumour immunity, we thoroughly examined the correlation between these immune-related genes and AVPR2." (PMID 36998036, 2023). "Then, to further elucidate the role of AVPR2 in tumour immunity, we explored the relationship between AVPR2 expression and different immune subtypes of HNSCC." (PMID 36998036, 2023). "In some studies, AVPR2 can promote tumour cell proliferation, but in other studies, it plays a protective role." (PMID 36998036, 2023). "Studies have revealed that amongst the 6 identified target genes, Dpp6 and Pcdh9 were Tumor suppressor genes (TSGs) and Avpr2, Cyp4a12b, Dpp6, Gria2, Pcdh9 and Tspan11 were key tumor-related transcripts that can regulate various pathways during carcinogenesis." (PMID 35263365, 2022). "AVPR2 activation increased cell proliferation of clear cell RCC cell lines, and AVPR2 abnormal expression was detected in ccRCC and associated with the tumor grade 15,16." (PMID 33193899, 2020). "In this study, we figure out AVPR2 expression is decreased in tumor tissue and relevant to a better prognosis." (PMID 33193899, 2020). "Our team has reported that the vasopressin analog desmopressin, a selective agonist for the vasopressin receptor 2 (AVPR2), significantly reduced tumor cell growth and migration in AR-negative CRPC." (PMID 31998646, 2019). "Furthermore, in AVPR2-expressing tumours, agonists that selectively act on AVPR2 exhibit robust antitumour activity." (PMID 36998036, 2023). "Therefore, it is important to further explore the role of AVPR2 and tumour-infiltrating B cells in HNSCC." (PMID 36998036, 2023). "After excluding the potential effects of age, sex, tumour stage, and tumour purity in 428 HNSCC patients, we found that compared with HNSCC patients with low AVPR2 expression, HNSCC patients with high AVPR2 expression had a lower risk of death (HR 0.484, 95% CI 0.293–0.798, P = 0.004)." (PMID 36998036, 2023). "Future studies are needed to explore the role of AVPR2 and tumour-infiltrating B cells in HNSCC." (PMID 36998036, 2023). "Interestingly tumors may produce and secrete AVP, in addition to expressing AVPR2, thus favoring self-maintenance and proliferation of the tumor itself." (PMID 39125971, 2024). "In addition, recent reports have shown that the AVPR2 gene may play an important role in tumour immunity." (PMID 36998036, 2023). "However, in some other studies, AVPR2 may inhibit tumour proliferation by activating the canonical adenylate cyclase/cAMP/PKA axis in tumour cells." (PMID 36998036, 2023). "Hence, our results suggest that AVPR2 may influence HNSCC tumour immunity primarily by modulating the tumour immune microenvironment, with AVPR2 regulation of tumour-infiltrating B cells possibly being a key link." (PMID 36998036, 2023). "Materials and Methods: IHC and PT-PCR were used to detect ENaCα, β, γ, AVPR2, AQP2, and MR expression in the primary tumor and peritumoral tissues." (PMID 33193899, 2020). "AVPR2 antagonists or gene silencing reduced cell viability of 786-O and Caki-1, and also decreased RCC tumor growth in mouse xenograft models." (PMID 33193899, 2020). "In addition, AVPR2 may play a role in HNSCC immune modulation, and the regulation of tumour-infiltrating B cells by AVPR2 may be a key link." (PMID 36998036, 2023).
tumor (continued). "Moreover, AVPR2 may play a role in HNSCC immune modulation, and the regulation of tumour-infiltrating B cells by AVPR2 may be a key link." (PMID 36998036, 2023).
cancer (25 papers, 2013 to 2024). A tumor composed of atypical neoplastic, often pleomorphic cells that invade other tissues. "Agonist activation of AVPR2 present in various human cancer cell lines has been associated with triggering of antiproliferative signaling pathways involving canonical adenylate cyclase/cAMP/PKA axis activation." (PMID 31998646, 2019). "We have previously demonstrated that the vasopressin type 2 receptor (AVPR2) antagonist tolvaptan reduces cell proliferation and invasion and triggers apoptosis in different human cancer cell lines." (PMID 39125971, 2024). "In this study, we performed a comprehensive analysis of the AVPR2 gene in HNSCC using public datasets from The Cancer Genome Atlas and Gene Expression Omnibus." (PMID 36998036, 2023). "In particular, in the case of AVPR2 in cancer cells, it can be hypothesized that cell behavior may differ, depending for instance on the type of cancer or on the possible presence of receptor mutations." (PMID 39125971, 2024). "Nevertheless, additional pre-clinical studies are needed in order to confirm these preliminary data and to further clarify the molecular mechanisms that are involved in AVPR2 antagonism, as well as the lowest effective dose of tolvaptan against cancer progression." (PMID 39125971, 2024). "The expression of AVPR2 has been reported in a variety of cancers." (PMID 36998036, 2023). "The expression of ENaCα, β, γ, AQP2, AVPR2, and MR decreased in cancer tissue." (PMID 33193899, 2020). "Moreover, while AVPR2 mutations, as expected, led to constitutive activity, none of the representative receptors with cancer mutations displayed constitutive activation as reported by cAMP assays." (PMID 31337866, 2019). "Taken together, it seems that CREB activation is not prominent after AVPR2 selective agonist action on cancer cells, being favored certain antiproliferative signals." (PMID 31998646, 2019).
genetic diseases (6 papers, 2017 to 2022). "X‐linked nephrogenic diabetes insipidus (NDI) is a rare genetic disorder that is associated with marked polyuria due to mutations in the gene that codes for the V2 vasopressin receptor (gene symbol: Avpr2)." (PMID 28108651, 2017). "Congenital nephrogenic diabetes insipidus (CNDI) is a genetic disorder caused by mutations in arginine vasopressin receptor 2 (AVPR2) or aquaporin 2 genes, rendering collecting duct cells insensitive to the peptide hormone arginine vasopressin stimulation for water reabsorption." (PMID 33804115, 2021).
renal disease (6 papers, 2017 to 2024). "Congenital nephrogenic diabetes insipidus (CNDI) is a rare renal disorder caused by mutations in arginine vasopressin receptor 2 (AVPR2) or aquaporin 2 (AQP2)." (PMID 32083042, 2020). "In regards, immunohistochemistry and RT-PCR experiments in renal disease confirmed a nearly significant decrease in AVPR2 protein and mRNA expression." (PMID 34903939, 2021). "Moreover, the relationship between AQP2 and AVPR2 and the localization of these proteins’ expression in dogs with renal disease have rarely been investigated." (PMID 34903939, 2021).
AVPR2 also shares sentences with these, for which no sentence is quoted: autosomal dominant polycystic kidney disease (22 papers); nephrogenic syndrome of inappropriate antidiuresis (10); Parkinson disease (7); infection (6); lung carcinoma (5); Renal cyst (5); Ascites (4); Cirrhosis (4); diabetes (3); Hypernatremia (3); kidney damage (3); liver cirrhosis (3); Bartter syndrome (2); brain tumor (2); cardiac hypertrophy (2); Fanconi anemia (2); heart disease (2); Hepatic cysts (2); Leigh syndrome (2); mitochondrial disease (2); Sepsis (2); septic shock (2); Stroke (2); syndrome of inappropriate antidiuretic hormone secretion (2); Alzheimer disease (1); autoimmune disease (1); autoimmune hyperthyroidism (1); bleeding disorders (1); cardiac arrest (1); cavernous hemangioma (1).
A further 49 diseases each share a sentence with AVPR2 in 1 paper.